TUG1 (taurine up-regulated 1)
Diseases named in the same sentence as TUG1 in open-access papers (continued):
Sharing a sentence is not in itself a finding about the gene and the disease.
tumor (continued). "Moreover, overexpression of lncRNA TUG1, a natural anti-tumor agent, is discovered in DOX-resistant OS cells, while downregulation of TUG1 by polydatincan promotes DOX-induced apoptosis in vitro and inhibits tumor growth in the DOX-resistant model in vivo by suppressing the AKT signaling pathway." (PMID 38516191, 2024). "We further explored the effects of Tug1 upregulation on the tumor immune microenvironments via flow cytometry and found that CD8+ T cells significantly increased and displayed stronger activation phenotypes with more production of IFN‐γ, IL‐2, and TNF‐α in sh‐Tug1 Hepa1‐6 cell‐bearing mice." (PMID 38981064, 2024). "lncRNAs with a demonstrated ability to regulate tumor metastasis (e.g., lincIRX5 and lincFOXF1) and lncRNAs with unclear functions (e.g., lincMTX2 and lincTNS1) might have the potential to regulate CRC liver metastasis in a manner similar to that of TUG1 and MALAT1." (PMID 28628609, 2017). "Thus, TUG1 regulation could alter VEGFA level, which in turn affects tumor angiogenesis." (PMID 27362796, 2016). "To investigate the relationship among TUG1, miR-524, and SIX1, we investigated the levels of TUG1, miR-524, and SIX1 in adjacent non-tumor, non-metastatic HCC, and metastatic HCC tissues." (PMID 35193488, 2022). "The results showed an increasing trend of TUG1 levels, a decreasing trend of miR-524-5p levels, and an increasing trend of SIX1 levels in adjacent non-tumor, non-metastatic HCC, and metastatic HCC tissues." (PMID 35193488, 2022). "Growing evidence revealed a negative correlation between TUG1 and miR-421 as a CRC tumor suppressor factor." (PMID 36333703, 2022). "Amongst them, TUG1 and linc-ROR were not detectable in plasma, ZFAS1 was significantly up-regulated in plasma of tumor patients, while GAS5 showed no significant changes." (PMID 29559565, 2018). "We found that TUG1 was up-regulated in HCC tissues than that in corresponding non-tumor tissues and was related to tumor size and BCLC stage." (PMID 26336870, 2015). "In addition, ∼70% of Notch1-positive GBM cells showed high expression of TUG1 in the perivascular regions, whereas in areas distant from tumour vessels, the majority of GBM cells expressed neither Notch1 nor TUG1." (PMID 27922002, 2016).
cancer (178 papers, 2014 to 2025). A tumor composed of atypical neoplastic, often pleomorphic cells that invade other tissues. "Taurine Upregulated Gene 1 (TUG1) is an lncRNA that is overexpressed in many types of cancer and has been implicated in resolving R-loops, thereby maintaining genomic integrity." (PMID 40654306, 2025). "TUG1 (Taurine-upregulated gene 1) is a long non-coding RNA recently linked to the development of various human cancers." (PMID 39479021, 2024). "TUG1 is also a relevant mediator of crosstalk between cancer-associated fibroblasts and OS cells in TME to promote invasion and distant metastasis, as detailed in a next section." (PMID 38835012, 2024). "Taken together, these data indicate that depletion of TUG1 caused both the accumulation of R-loops and RS during S phase in all of the cancer cell lines tested." (PMID 37607907, 2023). "The lncRNA TUG1 has been shown to be upregulated in many malignancies and its overexpression is closely linked to cancer prognosis." (PMID 37754243, 2023). "The cytoplasmic lncRNA TUG1 regulated mutation in multiple advanced cancers 1 (PTEN) expression through binding miRNAs." (PMID 37239407, 2023). "Previous studies have shown the association of HOTAIRM1, CRNDE, and TUG1 expression in the pathogenesis of various cancers, including ALL." (PMID 37303492, 2022). "Cancer-associated fibroblasts (CAFs)-secreted exosomes promoted migration, invasion, and glycolysis in HepG2 cells by releasing TUG1." (PMID 35193488, 2022). "In this study, we investigated the role of cancer-associated fibroblasts (CAFs)-derived exosomal TUG1, SIX1 and miR-524-5p in the migration, invasion, and glycolysis in HCC cells." (PMID 35193488, 2022). "For instance, exosomal TUG1 derived from cancer-associated fibroblasts promotes metastasis and glycolysis in HCC through the miR-524-5p/SIX1 axis." (PMID 35581586, 2022). "Taurine up-regulated gene 1 (TUG1) is a cancer-associated long noncoding RNA (lncRNA) and engages in the development of spinal cord injury (SCI), a suffering neuropathological disorder." (PMID 34517787, 2021). "In our study, the results suggest that high TUG1 expression is significantly associated with worse OS in patients with malignant tumors, which is consistent with the conclusions drawn from previous studies." (PMID 33747256, 2021). "We further wanted to test the physiological role of TUG1 subcellular localization in cancer cell lines, as it has been implicated in many cancers." (PMID 34083519, 2021). "Taurine upregulated gene 1 (TUG1) is an oncogenic lncRNA that is associated with chemoresistance in various cancers." (PMID 34425750, 2021). "Previous studies reported that TUG1 regulates cell proliferation and migration and is implicated in the development of various cancers, including osteosarcoma, gastric cancer, lung cancer, and other cancers." (PMID 33889601, 2021). "TGF-β from cancer-associated fibroblasts (CAFs) can up-regulate the expression of TUG1, and the crosstalk between CAFs and OS activate TUG1 to generate lncRNA TUG1 and promote the metastasis of OS." (PMID 33109235, 2020). "The PABPN1–NEXT–exosome pathway thus represents one possibility of how nuclear polyadenylated lncRNAs, among them also cancer-associated lncRNAs like TUG1 and NEAT1, are targeted for degradation." (PMID 32340118, 2020). "Apart from our findings, dysregulated TUG1 has been reported to be implicated with chemoresistance in other cancers." (PMID 30519392, 2018). "The mechanism underlying the relationship between elevated lncRNA TUG1 expression and poor prognosis in cancer patients need to be further elucidated." (PMID 28548946, 2017). "We mainly discussed the expression of TUG1 associate with prognosis, and metastasis of cancer patients." (PMID 29029461, 2017). "No further analysis concerning the association between the lncRNA TUG1 expression and specific cancer was conducted for the limited included studies." (PMID 29245996, 2017).
cancer (continued). "In the subgroup analysis by cancer type, elevated TUG1 expression was associated with poorer survival in cancer patients with high TUG1 expression subgroup but better survival in patients with low TUG1 expression subgroup." (PMID 29029461, 2017). "Increasing clinical studies indicate that elevated expression of lncRNA TUG1 is closely linked with poor prognosis and high risk of cancer metastasis in many types of carcinomas." (PMID 28548946, 2017). "Increases the invasive and metastatic ability of CRC cells through activating EMT process and TUG1 overexpression indicates poor survival rates and a higher risk for cancer metastasis." (PMID 27888635, 2017). "In recent years, numerous studies discovered that LncRNA TUG1 expression was positively associated with prognostic outcomes in cancer patients, however, the results was controversial." (PMID 29245996, 2017). "Thirdly, this meta-analysis was only performed to explore the association between the lncRNA TUG1 expression and prognosis of patients in various cancers." (PMID 29245996, 2017). "In summary, our meta-analysis provides evidence that increased TUG1 expression is associated with poorer survival in cancer patients with high TUG1 expression but better survival in patients with low TUG1 expression." (PMID 29029461, 2017). "A significant association was observed between TUG1 and OS in other cancer patients (pooled HR=1.41, 95% CI: 1.01-1.98)." (PMID 28977959, 2017). "Long noncoding RNAs (lncRNAs) play crucial roles in tumorigenesis, and lncRNA taurine-upregulated gene 1 (TUG1) has been proven to be associated with several human cancers." (PMID 27485439, 2016). "To explore the competing functional roles of TUG1 in different cancers, we performed the functional enrichment analysis to identify TUG1 targeting hallmark processes in pan-cancers." (PMID 27580177, 2016). "We found that TUG1 removes pathological R-loops susceptible to DNA damage in cancer cells." (PMID 37607907, 2023). "TUG1 is a cancer-associated fibroblast (CAF)-derived exosomal lncRNA." (PMID 37754243, 2023). "At present, there are relatively fewer clinical studies on lncRNA TUG1, but existing studies suggest that lncRNA TUG1 may be an effective diagnostic or prognostic cancer biomarker." (PMID 34039257, 2021). "Moreover, the role of TUG1, an atherosclerosis-associated lncRNA, in various cancers has been previously studied." (PMID 34421622, 2021). "However, a significant association was found between relative expression of TUG1 and cancer subtype." (PMID 30866866, 2019). "And the results could encourage more researchers pay attention to the prognostic role of lncRNA TUG1 in cancers and further to explore the underlying mechanisms." (PMID 29245996, 2017). "Taurine upregulated 1 gene (TUG1) is a long non-coding RNA associated with several types of cancer." (PMID 29657297, 2017). "Furthermore, we found a significant unfavorable association between elevated lncRNA TUG1 and OS of cancer patients in China (HR = 1.96, 95% CI: 1.12–3.44, P = 0.018)." (PMID 28548946, 2017). "Expression of TUG1 is closely associated with cancer progression and therapy." (PMID 28872613, 2017). "Furthermore, the subgroups were analyzed based on the cancer type and revealed a significant association between TUG1 and OS in NSCLC (HR=0.49, 95% CI: 0.34-0.71)." (PMID 28977959, 2017). "Moreover, we also selected five representative disease lncRNAs (HOTAIR, MALAT1, H19, MEG3 and TUG1) that play key roles as oncogenic molecules associated with various cancers to investigate their occurrences at the top 5%-20% of the candidate lists." (PMID 28076842, 2017). "According to meta-analysis result, it can be found that the expression of TUG1 might be associated with poor overall survival in different cancers." (PMID 29145271, 2017).
cancer (continued). "Finally, six lncRNAs (DLEU2, HOTTIP, MALAT1, NEAT1, SNHG1, and TUG1), registered in Lnc2Cancer 2.0, a database offering comprehensive experimentally supported associations between lncRNA and human cancer, were selected as candidate lncRNAs for the diagnosis of HCC." (PMID 34185961, 2021). "One such lncRNA, taurine upregulated 1 (TUG1), has gained attention as a biomarker in cancer detection and prognosis due to its role in cell survival, mobility, transformation, aggressiveness, apoptosis, and drug sensitivity." (PMID 39465506, 2025). "TUG1 regulates the expression of genes associated with EMT, metastasis, and therapeutic resistance, affecting the adaptability of cancer cells." (PMID 41013839, 2025). "TUG1 can augment the chemoresistance of cancer cells by upregulating the expression of multidrug resistance (MDR) genes." (PMID 41013839, 2025). "Although the role of TUG1 in cancer cells has been elucidated, in this study we focused on analysing the proteins that associate with TUG1 under replication stress in normal cells." (PMID 40654306, 2025). "While most current research on TUG1 focuses on its role in human cancers, where it is known to encourage cancer cell growth, movement, and invasiveness, some studies also link TUG1 to neurodegenerative disease pathologies." (PMID 38543885, 2024). "As the knockdown of Tug1 promoted the phagocytosis function of macrophages toward cancer cells, we attempted to evaluate the impact of overexpression of miR‐340 in Hepa1‐6 cells on the phagocytosis of macrophages." (PMID 38981064, 2024). "The lncRNA TUG1 (Taurine upregulated 1) is abnormally expressed in many cancer types and reported as an oncogene promoting cell proliferation, glycolysis, metastasis, angiogenesis and chemoradioresistance." (PMID 38835012, 2024). "The results showed that the downregulation of Tug1 inhibited cancer cell proliferation, migration, and invasion, and promoted cell apoptosis." (PMID 38981064, 2024). "One example is represented by cancer-associated fibroblasts (CAFs)-derived TGF-beta, that is able to upregulate the expression of TUG1 in OS cells." (PMID 38835012, 2024). "In vitro studies indicate that TUG1 knockdown reduces neuronal apoptosis in oxygen–glucose deprivation (OGD) models, while decreased TUG1 expression is associated with worse cancer outcome metrics." (PMID 38502340, 2024). "Representative immunofluorescence images showed that the downregulation of Tug1 significantly increased the phagocytosis of cancer cells by macrophages derived from both the peritoneal cavity and bone marrow." (PMID 38981064, 2024). "believe that TUG1 accelerates cancer EMT by regulating the miR-26a-5p/MMP14/p38 MAPK/Hsp27 axis in vitro and in vivo." (PMID 39026978, 2024). "As Tug1 inhibits the phagocytosis function of macrophages toward cancer cells by promoting Cd47 expression, we further used the ENCORI/starBase to predict the potential binding sites of miRNAs in the 3′UTR of Cd47." (PMID 38981064, 2024). "The TUG1 (taurine-upregulated gene 1) lncRNA is overexpressed in many cancers, affecting cancer cell proliferation and apoptosis." (PMID 38203731, 2023). "Here, the authors show that the long noncoding RNA TUG1 resolves R-loops and reduces replication stress in cancer cells." (PMID 37607907, 2023). "The combined ROC curve of TUG1:UCA1 demonstrated high effectivity for the discrimination of subjects with cancer from healthy ones." (PMID 37569782, 2023). "Our data reveal a role of TUG1 as molecule important for resolving R-loop accumulation in cancer cells and suggest targeting TUG1 as a potent therapeutic approach for cancer treatment." (PMID 37607907, 2023). "Here, we report taurine upregulated gene 1 (TUG1) long noncoding RNA (lncRNA), which is highly expressed in many types of cancers, as an important regulator of intrinsic R-loop in cancer cells." (PMID 37607907, 2023).
cancer (continued). "In this study, we first evaluated TUG1 expression in various cancers and its correlation with patient prognosis." (PMID 37813900, 2023). "As a “star molecule,” lncRNA TUG1 has been widely reported in promoting cancer progression, regulating inflammatory response, nerve regeneration, and osteogenic differentiation, and plays an important role in a variety of diseases." (PMID 36658478, 2023). "ImmLnc online analysis results also indicated that TUG1 expression was perturbed in various cancers, including HNSC, KIRP, LIHC, LUAD, STAD, BLCA, and ESCA." (PMID 37813900, 2023). "TUG1 and PD-L1 were highly expressed in HCC tissues and HCC cancer cells, and high expression of TUG1 and PD-L1 was related to the poor prognosis of HCC patients." (PMID 37813900, 2023). "In conclusion, our data reveal an important function of TUG1 as an indispensable RNA molecule controlling R-loops in proliferating cancer cells." (PMID 37607907, 2023). "Numerous studies have demonstrated the critical role of lncRNA Taurine upregulated gene 1 (TUG1) in cancer initiation and progression." (PMID 35928868, 2022). "The results showed that TUG1 was markedly upregulated in GC compared with normal controls, and the high expression level predicted poor prognosis, especially in higher cancer stages and grades." (PMID 36157241, 2022). "For non‐small‐cell lung cancer, lncRNA TUG1 can enhance the sensitivity of cancer cells to chemotherapeutic drugs by interfering with miR‐221‐dependent PTEN inhibition." (PMID 35421276, 2022). "LncRNA TUG1 promotes tumor cell metastasis and epithelial-mesenchymal transition in a series of cancers." (PMID 35819532, 2022). "Overexpression of miR-195-5p abated the cancer-promoting function of TUG1 and curbed the profile of the HDGF/DDX5/β-catenin axis." (PMID 35014946, 2022). "Recent studies show that various lncRNAs, such as HOTAIR, MALAT1, NRAL and TUG1, play a pivotal role in the regulation of cancer cells’ oxidative stress, highlighting a possible crossroad between lncRNAs and ROS." (PMID 36077530, 2022). "This denotes that the cancer-promoting function of IGF2BP2 in CRC is achieved at least partially through the regulation of TUG1’s profile." (PMID 35014946, 2022). "TUG1 was reported to regulate Wnt/β-catenin signaling pathway to mediate the progression of multiple cancers, including CRC." (PMID 34030715, 2021). "In contrast, in healthy and cancer cell lines, intron-containing TUG1 and TERT RNAs were highly stable even after 4.5 h of transcription inhibition." (PMID 34083519, 2021). "Both TERT and TUG1 are upregulated in many cancers and thus represent important therapeutic targets." (PMID 34083519, 2021). "Although most studies have revealed the carcinogenic effects of this lncRNA, it has also been reported that compared with non-cancer samples, TUG1 is downregulated in non-small cell lung cancer samples 9-11." (PMID 34659578, 2021). "We conducted this meta-analysis to comprehensively confirm the prognostic effect of TUG1 in malignant tumors." (PMID 33747256, 2021). "The evaluation of the expression levels and functions of lncRNA TUG1 in cancer requires further research to provide a reference for accurate targeted therapy." (PMID 34039257, 2021). "In the present review, we evaluated the molecular mechanisms and clinical significance of lncRNA TUG1 in different cancer types." (PMID 34039257, 2021). "The lncRNA taurine upregulated gene 1 (TUG1) is a recently identified potential biomarker in cancer." (PMID 33747256, 2021). "Previous studies indicated that lncRNA taurine upregulated gene 1 (TUG1) played essential roles in human cancers." (PMID 34362467, 2021). "At present, the literature reviews on lncRNA TUG1 are mainly based on the classification of different cancers." (PMID 34039257, 2021).